TNF (tumor necrosis factor)
Diseases named in the same sentence as TNF in open-access papers (continued):
Sharing a sentence is not in itself a finding about the gene and the disease.
ischemic stroke (continued). "Furthermore, through network pharmacology and molecular docking, four core targets (MAPK3, TNF-α, MAPK14, and JNK) closely related to RPR’s treatment of ischemic stroke were identified, exhibiting strong affinity with two key active components of RPR: albiflorin (AF) and β-sitosterol (BSS)." (PMID 39771032, 2024). "The results showed significantly higher levels of MDA, IL-6, TNF-α, and lower expression of SOD in the ischaemic stroke group compared to the control group, indicating the involvement of oxidative stress and inflammation in the early pathological progression of ischaemic stroke." (PMID 38245621, 2024). "Therefore, the most significant 4 genes were PIK3CA, IL6, TNF, and KNG1, which means these molecules may function as important immune regulators in the inflammatory response following ischemic stroke." (PMID 35419038, 2022). "Antibodies against IL-1β and TNF-α were not evaluated in ischemic stroke patients." (PMID 34248961, 2021). "Finally, plasma TNFR1 and TNFR2 levels increased significantly in the acute phase after symptom onset in ischemic stroke patients compared to healthy controls whereas TNF, IL-1α, IL-1β, and IL-1Ra did not change." (PMID 32503645, 2020). "The melanocortin MC4 receptor agonist RO27-3225 (used to reduce expression of TNF-α, BAX, ERK1/2, JNK1/2, and cascapse-3 and counteract prolonged/recurrent inflammatory and apoptotic responses) provides neuroprotective function and promotes functional recovery in ischemic stroke." (PMID 31031649, 2019). "In other tissue contexts, recent reports indicate that progestin suppressed TNF-α induced proliferation and CCL2 secretion of endometrial stromal cells in vitro, while P4 prevented macrophage infiltration to brain endothelial cells by blocking CCL2 action after an ischemic stroke." (PMID 28966800, 2017). "Therefore, lowering the cytotoxic effects of TNF-toxic and IL-1β in the CNS by ANGPTL2 suppression may serve as an attractive therapeutic option in the acute phase of ischemic stroke." (PMID 27861531, 2016). "In conclusion, there is no consensus on the effect of TNF-α after ischemic stroke." (PMID 21040547, 2010). "However, it has not been clearly established whether TNF-α participates in the pathogenesis of ischemic stroke by regulating platelet reactivity." (PMID 35781632, 2022). "NF-κB activation is initiated when molecules such as TNF-α bind to TNF receptors, and the induction of NF-κB target genes requires phosphorylation of NF-κB proteins, such as p65; therefore, factors that modulate the activity of NF-κB may modulate the inflammatory process in ischemic stroke." (PMID 36559268, 2022). "In addition, it was shown that IL-6 might promote early clinical deterioration of ischemic stroke, and TNF-α did not play a role in early clinical deterioration." (PMID 35111052, 2021). "We showed that salivary TNF-α and IL-6 were significantly higher, whereas IL-10 content was statistically lower in both non-stimulated (NWS) and stimulated (SWS) whole saliva of ischemic stroke patients." (PMID 34433866, 2021). "In ischemic stroke patients, we demonstrate that plasma TNFR1 and TNFR2 levels increased in the acute phase after symptom onset compared to healthy controls, whereas TNF, IL-1α, IL-1β, and IL-1Ra did not change." (PMID 32503645, 2020). "Secondly, ischemic stroke, including MCAO, can trigger a cascading pathological noninfectious neuroinflammation and the subsequent excessive release of proinflammatory cytokines, including interleukin-1 (IL-1), tumor necrosis factor alpha (TNF-α), and interleukin-6 (IL-6)." (PMID 33551726, 2020).
pneumonia (393 papers, 2005 to 2026). An acute, acute and chronic, or chronic inflammation focally or diffusely affecting the lung parenchyma, caused by an infection in one or both of the lungs (by bacteria, viruses, fungi, or mycoplasma.). "This large-scale pharmacovigilance study, analyzing 7,176 reports, revealed substantial heterogeneity in pneumonia risk profiles among different TNF-α inhibitors, with important implications for clinical decision-making and patient management strategies." (PMID 40763141, 2025). "The inflammatory response in pneumonia is closely associated with the activation of several signaling pathways, particularly the tumor necrosis factor (TNF), nuclear factor kappa B (NF‐κB), and mitogen‐activated protein kinases (MAPKs) pathways." (PMID 40144560, 2025). "For HMPV, we and others have reported that higher TNF levels in nasopharyngeal aspirates and blood are associated with pneumonia and bronchiolitis severity, supporting a critical role for TNF in HMPV-induced lung pathology." (PMID 41346628, 2025). "Pneumonia was the predominant cause of hospitalization in both groups, mostly occurring under TNF or IL-23 inhibitor treatment, as previously reported." (PMID 40649154, 2025). "Across the four TNF-α inhibitors, we identified 36 Preferred Terms (PTs) associated with infective pneumonia-related adverse events, with infliximab having the highest number of PTs and golimumab the lowest." (PMID 40763141, 2025). "Zinc deficiency can also contribute to elevated FPP levels in pneumonia because the acute-phase response, driven by proinflammatory cytokines (IL-6, IL-1β, TNF-α), triggers metallothionein synthesis and sequesters zinc in the liver and immune cells." (PMID 40615660, 2025). "A migration of mitochondria to the perinuclear area has been observed during infection with Ectromelia virus (ECTV), the agent of mousepox, which causes severe pneumonia with cytokine storm driven by the TNF signaling pathway." (PMID 40141361, 2025). "Patient characteristics and incidence (number and percentage) of infective pneumonia adverse events associated with TNF-α inhibitors." (PMID 40763141, 2025). "In this study, the SLN formulation of DXMS-Pal (DXMS-Pal-SLNs) was developed and evaluated in reducing the secretion of pro-inflammatory cytokines, namely TNF-α and IL-6, mainly by alveolar macrophages for pneumonia-associated inflammation treatment." (PMID 39065575, 2024). "NF-κB upregulates TNF-α, which can damage capillary endothelial cells, thereby promoting microthrombosis and leading to ischemic necrosis, so TNF-α is associated with pneumonia severity." (PMID 38585701, 2024). "Legionella causes the severe pneumonia Legionnaires’ disease and predominantly affects individuals with a suppressed immune system, including those receiving therapeutic TNF blockade to treat autoinflammatory disorders." (PMID 37279255, 2023). "Therapies to treat IBD are associated with an increased risk of infection, as anti-TNF inhibitors are associated with an increase in pneumonia, but vaccination against pneumococcus is associated with a reduced risk of pneumonia." (PMID 37674503, 2023). "Of the various cytokines implicated, tumor necrosis factor (TNF) is a crucial driver of inflammation in IAV-induced pneumonia." (PMID 36851532, 2023). "Accumulating evidence has confirmed that M. pneumoniae-induced pneumonia is closely associated with an elevated production of proinflammatory cytokines, including tumor necrosis factor-α (TNF-α) and interleukin- (IL-) 1β and IL-6." (PMID 37894556, 2023). "The purpose of this review is to summarize the differences between TNF inhibitors and therapeutic immunomodulation on predisposition to pneumonia caused by select intracellular pathogens." (PMID 36159650, 2022). "These cytokines will cause the immune system to produce an excessive attack on the human body and cause severe pneumonia, which mainly include interleukin-6 (IL-6), interleukin-1 (IL-1), tumor necrosis factor-α (TNF-α), and so on." (PMID 36146616, 2022).
pneumonia (continued). "While LPS-induced acute pneumonia caused an increase in cytokine/chemokine mRNA expression, including that of IL-1β, -6, TNF-α, MCP-1, TauCl treatment attenuated IL-6, and TNF-alpha expression, but not IL-1β and MCP-1." (PMID 35448536, 2022). "The mechanisms behind inflammation in conditions treated with TNF blockade involve the same pathways used in response to intracellular pathogens, causing increased susceptibility and severity of pneumonia in people living with these diseases." (PMID 36159650, 2022). "In summary, our present findings demonstrate that enriched intestinal K. pneumonia is associated with the incidence of pneumonia in MM and contributes to pneumonia by synthesizing glutamine to promote TNF-α expression." (PMID 36077725, 2022). "We focused on TNFα since this proinflammatory cytokine is readily produced by AMs upon stimulation with Spneu and plays a major role in host defense during pneumonia caused by this pathogen." (PMID 36096803, 2022). "Despite screening and treating for TB infection prior to TNF inhibitor therapy, it remains a frequent cause of pneumonia after starting TNF inhibitor therapy." (PMID 36159650, 2022). "Hyperproduction of pro-inflammatory cytokines such as IL-1β, IL-6, IL-12, IFN-γ and TNF-α have been linked to the pathogenesis of tissue injury observed in SARS-CoV-2 induced pneumonia seen in humans." (PMID 34929014, 2021). "A recent human study demonstrated that serum IL-6 and TNF levels are associated with early mortality of patients with pneumonia." (PMID 29922273, 2018). "Lung neutrophils from mice with pneumonia showed increased expression of genes that encode a number of mediators, including the important pro-inflammatory cytokines IL-1α, IL-6, TNF and CXCL1 (KC)." (PMID 28900269, 2017). "Prednisone has been associated with pneumonia, and cyclophosphamide, azathioprine and newer biologic agents such as tumor necrosis factor (TNF)-α blockers have been shown to confer an increased risk of infection." (PMID 26048579, 2015). "For TNF-α −238A/G polymorphism and pneumonia risk, there was also statistically significant between-study heterogeneity (Pheterogeneity = 0.0009 and I2 = 74%)." (PMID 23577187, 2013). "Higher levels of plasma tumor necrosis factor, another marker of systemic inflammation, were also associated with an increased risk of pneumonia." (PMID 23457535, 2013). "Previous studies have assessed the associations between TNF-α polymorphisms and the risk and outcomes of pneumonia." (PMID 23577187, 2013). "This meta-analysis of 13 studies systematically evaluated the associations between TNF-α −308A/G, −238A/G polymorphisms and risk and mortality of pneumonia." (PMID 23577187, 2013). "Seven studies (2235 cases and 2673 controls) studied the association between TNF-α −238A/G polymorphism and pneumonia risk." (PMID 23577187, 2013). "Seven studies identified the association between TNF-α −308A/G polymorphism and pneumonia mortality risk." (PMID 23577187, 2013). "Several studies evaluated the associations of tumor necrosis factor-α (TNF-α) polymorphisms with pneumonia in different populations." (PMID 23577187, 2013). "Nevertheless, no published studies analyzed the relationship between −238A/G polymorphism and TNF-α production in pneumonia patients." (PMID 23577187, 2013). "Similar to the case with other intracellular bacterial pathogens, such as Listeria monocytogenes, receipt of a TNF-α antagonist is emerging as a risk factor for pneumonia from Legionella spp." (PMID 23092579, 2012). "First, inhibition of TNFα in murine models of pneumonia caused by several respiratory pathogens, including Klebsiella pneumoniae and Streptococcus pneumoniae, resulted in a strongly enhanced bacterial outgrowth." (PMID 16595015, 2006). "Tumour necrosis factor (TNF) is crucial for the control of mycobacterial infection as TNF deficient (KO) die rapidly of uncontrolled infection with necrotic pneumonia." (PMID 16285886, 2005).
pneumonia (continued). "For example, MTX can lead to elevated liver enzymes, pneumonia, and gastrointestinal discomfort; TNF inhibitors have been associated with demyelinating lesions; and JAK inhibitors may increase the risk of herpes zoster." (PMID 40124380, 2025). "The levels of cytokines in bronchoalveolar lavage fluid (BALF) is closely associated with pulmonary inflammation, elevated levels of interleukin(IL)-6 and tumor necrosis factor-alpha (TNF-α) have been documented as being closely associated with the severity of pneumonia." (PMID 40406149, 2025). "For example, anti-TNF medications may increase the risk of infections, such as pneumonia, but newer biologics or IL-12/23 inhibitors have better safety profiles regarding infection risk." (PMID 37674500, 2023). "In a prospective, population-based cohort of American elderly, higher baseline levels of tumor necrosis factor alpha (TNF-α) and interleukin 6 (IL-6) were associated with an increased pneumonia risk during follow-up, even after adjustment for traditional risk factors and comorbidities." (PMID 35757724, 2022). "Because of the history of pneumonia, she was started on CTLA4Ig, a drug with a lower risk of serious infections than TNF inhibitors, in November Y. However, one week after introducing CTLA4Ig, scleritis in the right eye worsened and macular oedema became apparent." (PMID 35008766, 2021). "Serum IL-6 and TNF levels are associated with mortality of patients with pneumonia." (PMID 33057343, 2020). "PD’s potent inhibition on TNF-α production induced by PRRSV infection or LPS indicates that PD could attenuate pneumonia caused by PRRSV infection and accompanied secondary bacterial infection." (PMID 30469357, 2018). "Consequently, little attention has been drawn to the issue of RTIs in patients receiving TNF antagonists despite observations that LRTIs, and specifically pneumonia, are among the most common serious infections associated with the use of these agents." (PMID 29788248, 2018). "TNF-α participates in the lung injury associated with severe pneumonia." (PMID 30157804, 2018). "Similarly to C. pneumoniae-induced pneumonia, W. chondrophila-induced pneumonia was associated with the production of pro-inflammatory cytokines such as IL-6 and TNF in the lungs, and IL-6 and IL12p40 in the blood." (PMID 26950066, 2016). "In patients with severe pneumonia, the IL-6 levels were positively associated with high levels of leukocytes while the levels of TNF and IL-1β were associated with monocytes, possibly related to the recruitment and differentiation of macrophages at the site of inflammation." (PMID 27905908, 2016). "Eleven studies determined the association between TNF-α −308A/G polymorphism and pneumonia risk." (PMID 23577187, 2013). "Building on existing research, this study hypothesizes that ganodermanontriol can effectively alleviate pathological changes and inflammatory responses associated with acute pneumonia by modulating the phosphorylation and activation of the TNF/NF‐κB/MAPK signaling pathways." (PMID 40144560, 2025). "However, in the progression of pneumonia, cytokine storms caused by excessive responses of M1-type macrophages and the secretion of excessive cytokines such as tumor necrosis factor-alpha (TNF-α), interleukin-1 beta (IL-1β), interleukin-6 (IL-6), and other factors can be fatal." (PMID 37176064, 2023). "Similarly, other studies conducted in vitro show that mixing ascorbic acid with monocytes isolated from the peripheral circulation of patients with underlying pneumonia resulted in the diminished production of the proinflammatory cytokines TNF-α and IL-6 and the augmentation of IFN levels." (PMID 36004958, 2022). "Indeed, in pneumonia caused by Klebsiella pneumonia murine model, pro-inflammatory cytokines such as TNF-α, IL-1, and IL-17 are required for bacteria clearance from the lungs, whereas the anti-inflammatory cytokine IL-10 impairs host defense in this infection model." (PMID 29166668, 2017).
pneumonia (continued). "Therefore, it was biologically plausible that −308A/G polymorphism which could affect TNF-α level might influence the susceptibility to pneumonia and mortality risk." (PMID 23577187, 2013). "Therefore, we did this meta-analysis to determine whether TNF-α polymorphisms were associated with an increased risk of pneumonia or higher pneumonia mortality." (PMID 23577187, 2013). "During the initial phases of pneumonia, alveolar macrophages release inflammatory cytokines such as tumor necrosis factor-α (TNF-α), IL-10, and IL-6." (PMID 41018059, 2025). "Numerous studies have shown that levels of TNF‐α, IL‐1β, and IL‐6 are significantly elevated in the serum or bronchoalveolar lavage fluid of patients with acute pneumonia or in LPS‐induced animal models." (PMID 40144560, 2025). "Intratracheal injection of Pg culture supernatant significantly exacerbated pneumonia by increasing the production of TNF-α and IL-17, which indicates the importance of virulence factors produced by Pg." (PMID 40496020, 2025). "Previous reports on pneumonia patients showed that high serum levels of inflammatory cytokines, such as TNF-α, have been correlated with worse outcomes in community-acquired pneumonia patients." (PMID 40508859, 2025). "This study aimed to evaluate the role Heat shock protein-70 (HSP-70) and Tumor necrosis factor alpha (TNF-α) as predictors of acute respiratory distress syndrome (ARDS) in children with pneumonia." (PMID 41382116, 2025). "Infective pneumonia represents a significant clinical challenge in IBD patients receiving TNF-α inhibitors, stemming from both disease-related immunosuppression and drug-induced alterations in immune response." (PMID 40763141, 2025). "To obtain an initial understanding of how SRT1720 affects the inflammatory response in the airways during Klebsiella-induced pneumonia, we measured cytokines (IL-6, TNF-α) and chemokines (CXCL1 and CXCL2) in BALF obtained 24 or 42 h after infection." (PMID 41096578, 2025). "Serum inflammatory cytokine assays indicated significantly elevated levels of TNF-α, IL-1β, and IL-6 in the pneumonia group compared to the control group (p < 0.001), suggesting that pathogen infection triggered a systemic inflammatory response." (PMID 41300746, 2025). "This vaccine led to a 60% survival rate and reduced bacterial colonization in the spleen and lungs, and it lowered the pro-inflammatory cytokines (TNF-α, IL-6, IL-12) in a pneumonia model." (PMID 40076637, 2025). "The most significant elevation of plasma proinflammatory cytokines (IL-6, IL-1β, MCP-1, IP-10 and TNF-α) at 5 dpi were also detected in Subjects 03 and/or 04, suggesting more severe pneumonia-induced systemic inflammation." (PMID 41157643, 2025). "In sepsis and pneumonia models, prophylactic vaccination produced significant reductions in lung bacterial colonization and the levels of pro-inflammatory cytokines (IL-6, TNF-α and IL-1β), resulting in 100% survival over 14 days." (PMID 40076637, 2025). "In burn‐ALI mice with secondary pneumonia, CuMPBA restored lung architecture, suppress TNF‐α/IL‐1β/IL‐6 levels, and modulated inflammatory pathways by activating Nrf2 while inhibiting NF‐κB." (PMID 40956292, 2025). "After matching for age, pneumonia, APACHE II, LIPS, and PaO2/FiO2, DS and TNF-α were shown to be independently associated with the future development of ARDS." (PMID 40404729, 2025). "In children with pneumonia, the development of ARDS is associated with elevated serum levels of heat shock protein-70, elevated TNF-alpha, bacterial biofilm formation, respiratory acidosis, and a low Pa O2/FiO2 ratio." (PMID 41382116, 2025). "This study aimed to evaluate the role HSP-70 and TNF-α as predictors of ARDS in children with pneumonia with correlation of clinical data, biological, and inflammatory biomarkers." (PMID 41382116, 2025).